PLOD2 (procollagen-lysine,2-oxoglutarate 5-dioxygenase 2)
Diseases named in the same sentence as PLOD2 in open-access papers (continued):
Sharing a sentence is not in itself a finding about the gene and the disease.
pancreatic cancer (5 papers, 2019 to 2024). "In a hypoxic environment, increased PLOD2 expression levels promote the migration of pancreatic cancer cells by remodeling the extracellular matrix." (PMID 35560794, 2022).
colon cancer (4 papers, 2018 to 2024). "Overexpression of the cell adhesion molecule L1 induces higher expression of ezrin-dependent PLOD2 by reducing SMAD2/3 in colon cancer, which stimulates cell proliferation, tumorigenesis, and liver metastasis." (PMID 39068670, 2024). "In DLD1 colon cancer cells PLOD2 and CLPTM1L mRNA expression was downregulated after Evi/Wls silencing by shmirRNA." (PMID 29453334, 2018). "In HT29 colon cancer cells, mRNA expression of PLOD2, HADH and LCOR as well as AXIN2 as a canonical control target was downregulated upon treatment with the Porcupine inhibitor LGK974." (PMID 29453334, 2018). "Taken together, these experiments confirmed PLOD2, HADH, and LCOR as non-canonical Wnt targets that depend on Wnt secretion but not on β-catenin in colon cancer cell lines as well as primary colon cancer cells and MEFs." (PMID 29453334, 2018). "Independent experiments confirmed several target genes, including PLOD2, HADH, LCOR and REEP1 as non-canonical target genes in various colon cancer cells." (PMID 29453334, 2018). "Silencing of ATF2 revealed downregulation of PLOD2, HADH, LCOR and REEP1 mRNA expression; thus suggesting ATF2 as the transcription factor in non-canonical Wnt signaling in colon cancer cells." (PMID 29453334, 2018).
breast tumor (3 papers, 2017 to 2019). "qPCR array showed that adipocytes exhibited a significant increase in PLOD2 and collagen I expression when cocultivated with breast tumor cells." (PMID 31170987, 2019). "In addition to tumour cells, stromal cells, such as fibroblasts, also contribute to the up-regulation of PLOD2 in hypoxic breast tumour and finally lead to the remodelling of the ECM." (PMID 28507454, 2017). "Moreover, increased linearity degree of collagen at the invasive front was observed in invasive breast cancer patients, and PLOD2 expression in peritumoral adipose tissue was positively correlated with the PAI-1 expression in the corresponding breast tumor tissue." (PMID 31170987, 2019).
keloid (3 papers, 2020 to 2023). An irregularly shaped, elevated mark on the skin caused by deposits of excessive amounts of collagen during wound healing. "The increased expression of PLOD1 and PLOD2 regulates the expression of 5-hydroxylysine in keloid tissue." (PMID 35222522, 2021).
laryngeal carcinoma (3 papers, 2019 to 2022). Carcinoma that arises from the laryngeal epithelium. "To validate the contribution of PLOD2 of laryngeal cancer to chemoresistance, we used nude mice model." (PMID 31455288, 2019). "By analyzing the PLOD2 mRNA expression levels and Wnt-regulated gene signatures in laryngeal cancer cells, we found that PLOD2 overexpression upregulated the downstream genes of the Wnt signaling pathway." (PMID 31455288, 2019). "Altogether, these data suggest that PLOD2 could enhance the CSC-like phenotype of laryngeal cancer cells and that PLOD2 plays a novel role in malignancies." (PMID 31455288, 2019). "However, previous studies in laryngeal carcinoma suggested that PLOD2 enhanced CD44 expression via activation of the Wnt-signaling pathway, which may be a possible explanation for GBM as well." (PMID 35682709, 2022). "However, the role of PLOD2 in laryngeal cancer is unknown, and the mechanism of PLOD2 in malignancies remains largely unexplored." (PMID 31455288, 2019). "Hence, PLOD2 may increase the CSC-like properties of cells in laryngeal cancer by activating the Wnt/β-catenin signaling pathway, which is supported by previous reports." (PMID 31455288, 2019). "We assumed that PLOD2 is an indicator of prognosis in LSCC patients and plays a key role in the progression of laryngeal cancer." (PMID 31455288, 2019).
oral squamous cell carcinoma (3 papers, 2021 to 2025). "In addition, PLOD2 activated integrin β1 through IL-6/STAT3 signaling to promote invasion and metastasis in oral squamous cell carcinoma." (PMID 38184566, 2024).
osteoarthritis (3 papers, 2017 to 2025). A noninflammatory degenerative joint disease occurring chiefly in older persons, characterized by degeneration of the articular cartilage, hypertrophy of bone at the margins and changes in the synovial membrane. "In chondrocytes, we validated a circRNA deriving from PLOD2, a gene which forms collagen crosslinks and was differentially expressed in a model of osteoarthritis-related synovial fibrosis." (PMID 28842720, 2017).
Osteopenia (3 papers, 2012 to 2024). Osteopenia is a term to define bone density that is not normal but also not as low as osteoporosis. "Bruck syndrome Type 2 stems from a homozygous mutation in the PLOD2 gene and exhibits characteristics such as osteopenia, congenital contractures with pterygia, femoral bowing, club feet, postnatal shorty stature, severe limb deformity, and progressive scoliosis." (PMID 38983978, 2024).
osteoporosis (3 papers, 2022 to 2025). A condition of reduced bone mass, with decreased cortical thickness and a decrease in the number and size of the trabeculae of cancellous bone (but normal chemical composition), resulting in increased fracture incidence. "IL6, CXCR4, IGF1, and PLOD2 played crucial roles in weightlessness osteoporosis, which provided a theoretical basis for the pathogenic mechanism and treatment of weightlessness osteoporosis." (PMID 35479581, 2022). "Among them, IL6, CXCR4, IGF1, and PLOD2 were finally included in this study for follow-up analysis, because the relationships between these genes and weightlessness osteoporosis remained unclear, which was worth further analyzing." (PMID 35479581, 2022). "This study firstly found that PLOD2 played a momentous role in mediating the progression of weightlessness osteoporosis." (PMID 35479581, 2022).
prostate carcinoma (3 papers, 2014 to 2025). A carcinoma that arises from epithelial cells of the prostate gland. "Notably, PLOD2, a lysyl hydroxylase involved in collagen cross-linking, has been recently implicated in ECM stiffening and metastasis across various cancers, including prostate cancer." (PMID 40943497, 2025). "A similar hypoxia-dependent effect on CXCR4, VEGF and PLOD2 induction was observed in response to suppressed Rb expression in LNCaP prostate cancer cells suggesting that this observation is not cell type specific." (PMID 24919196, 2014).
squamous cell carcinoma (3 papers, 2017 to 2024). A carcinoma arising from squamous epithelial cells. "In high-grade squamous intraepithelial lesions and normal cervical cells, PLOD2 expression is higher in squamous cell carcinoma." (PMID 39840054, 2024). "It has been shown that PLOD2 is able to activate β1 integrin expressed in the head and neck squamous cell carcinomas." (PMID 34421605, 2021). "Prior studies have shown that PLOD2 is expressed at higher levels in squamous cell carcinoma compared to high-grade squamous intraepithelial lesions and normal cervical cells, primarily due to its role in catalyzing the hydroxylation of lysine residues in collagen molecules." (PMID 39840054, 2024).
astrocytomas (2 papers, 2017). "Staining for PLOD2 protein was absent or weak in non-neoplastic brain tissue samples and grade II astrocytomas, increased in grade III astrocytomas and enhanced to an even greater extent in GBM." (PMID 29165393, 2017).
diabetes (2 papers, 2017 to 2024). "In addition, alteration of MMPs-9, −13 and −14 expression, PARP-1, HIF1α, and increased collagen biosynthesis as well as collagen cross-linking protein, P4HA1 and PLOD2 were observed along with diminished vascular density in diabetic kidney." (PMID 28883608, 2017).
head and neck squamous cell carcinoma (2 papers, 2021). A squamous cell carcinoma that arises from any of the following anatomic sites: lip and oral cavity, nasal cavity, paranasal sinuses, pharynx, larynx, and salivary glands. "Recent studies have shown that in head and neck squamous cell carcinoma (HNSCC), integrin β1 is more stable after Plod2-hydroxylated modification, and is subsequently recruited to the cell membrane to regulate tumor cell movement, thereby promoting tumor invasion and metastasis." (PMID 34179084, 2021). "PLOD2 mRNA and protein levels were highly increased in tumor tissues of head and neck squamous cell carcinoma (HNSCC) (p < 0.001) and OSCC compared with those in nontumor tissues (p < 0.001)." (PMID 34944486, 2021).
triple-negative breast carcinoma (2 papers, 2021 to 2024). An invasive breast carcinoma which is negative for expression of estrogen receptor (ER), progesterone receptor (PR), and human epidermal growth factor receptor 2 (HER2). "Besides, the levels of PLOD1, PLOD2 and PLOD3 were higher in triple negative breast cancer (TNBC) patients than non-TNBC patients." (PMID 39068670, 2024).
varicocele (2 papers, 2023 to 2025). A condition characterized by the dilated tortuous veins of the spermatic cord with a marked left-sided predominance. "This increased stability leads to the upregulation of PLOD2 expression, which plays a significant role in regulating the proliferation and apoptosis of GC-2 cells (mouse germ cells) under oxidative stress conditions induced by varicocele." (PMID 40949795, 2025).
adhesive capsulitis (1 paper, 2016). "In the present study, we quantified the mRNA expression of the TGFβ1, TGFβR1, LOX, PLOD1, PLOD2, COMP, FN1, TNC and TNXB genes in glenohumeral synovium/capsule samples collected from patients with adhesive capsulitis and from controls." (PMID 27438566, 2016).
amoebiasis (1 paper, 2021). "Functional annotations of PLOD2 and PLOD3 indicated that they are involved in protein digestion and absorption, amoebiasis, and AGE-RAGE signaling pathways in diabetic complications." (PMID 35265665, 2021). "The functional annotations of PLOD2 and PLOD3 were protein digestion and absorption, amoebiasis, and AGE-RAGE signaling pathways in diabetic complications." (PMID 35265665, 2021).
arrhythmogenic right ventricular cardiomyopathy (1 paper, 2024). "PLOD2 appeared to be highly enriched in arrhythmogenic right ventricular cardiomyopathy and in the complement and coagulation cascades according to GSEA results and functional KEGG pathway analysis." (PMID 38431620, 2024).
brain arteriovenous malformations (1 paper, 2018). "Dysregulation of PLOD2 is associated with brain arteriovenous malformations and cancer progression." (PMID 30003082, 2018). "PLOD2 is overexpressed in brain arteriovenous malformations (bAVM), and the levels of PLOD2 expression correlated with bAVM size." (PMID 30003082, 2018).
cervical squamous cell carcinoma (1 paper, 2017). A squamous cell carcinoma arising from the cervical epithelium. "An analysis of a representative data set (Zhai cervix) revealed that PLOD2 mRNA expression levels were significantly higher in cervical squamous cell carcinoma than in cervix squamous epithelium." (PMID 28507454, 2017).
colon adenocarcinoma (1 paper, 2023). "Moreover, in the study of Deng, PLOD3, as a member of the PLODs family, is considered to be related to immune cell infiltration and genomic instability in colon adenocarcinoma, which makes us wonder whether PLOD2 also plays the same role in MSI GC." (PMID 35789544, 2023).
contracture (1 paper, 2024). Prolonged shortening of the muscle or other soft tissue around a joint, preventing movement of the joint. "Interest turned to the genetic variations in the genes for enzymes processing and trafficking type I collagens and were rewarded by the discovery of Lysyl Hydroxylase 2 coded by PLOD2 as a cause of OI with congenital joint contractures (Bruck syndrome type 2)." (PMID 38942908, 2024).
craniosynostosis (1 paper, 2017). Craniosynostosis is defined as the premature fusion of one or more cranial sutures leading to secondary distortion of skull shape resulting in skull deformities with a variable presentation. "In family 1020, one of the affected sisters also identified with a PLOD2 mutation, had in addition to bone fragility and congenital contractures, an unusual association of craniosynostosis and microcephaly with intellectual disability." (PMID 28116328, 2017).
Dry skin (1 paper, 2023). Skin characterized by the lack of natural or normal moisture. "It is interesting, that most disorders have additional skin manifestations such as dry skin in both ARC syndrome and collagen VI disorders, and fragile skin in patients with PLOD2, FKBP10 and PLOD3 mutations." (PMID 37686358, 2023).
endothelial dysfunction (1 paper, 2021). In vascular diseases, endothelial dysfunction is a systemic pathological state of the endothelium (the inner lining of blood vessels) and can be broadly defined as an imbalance between vasodilating and vasoconstricting substances produced by (or acting on) the endothelium. "The perspective of the current study would be to perform more experiments to unveil mechanistic and functional characteristics of PLOD2 and ENG1, which might provide an in-depth understanding of endothelial dysfunction." (PMID 33692478, 2021).
fibrosis (1 paper, 2020). the formation of excess fibrous connective tissue in an organ or tissue in a reparative or reactive process. "Collectively, the mRNA, as well as the protein levels, showed effective PLOD2 repression, even after 10 days of continuous expression stimulation, for both ZF-SKDs as well as for ZF7-M.SssI in our fibrosis model." (PMID 32455614, 2020).
Human papillomavirus infection (1 paper, 2022). "And the co-expression genes of PLOD2 and DSG2 also enriched in the Human papillomavirus infection which is inseparable with CC development." (PMID 35154316, 2022).
intrahepatic cholangiocarcinoma (1 paper, 2025). A carcinoma that arises from the intrahepatic bile duct epithelium in any site of the intrahepatic biliary tree. "Based on the training and validation cohorts of intrahepatic cholangiocarcinoma (ICA) bulk transcriptomes, seven metabolic enzymes were confirmed to be overexpressed in cases with poor prognosis: FH, MAT2B, PLOD2, PLOD1, PDE6D, ALDOC, and NT5DC3." (PMID 40034261, 2025). "Univariate logit binomial analysis, with the outcome being the proliferative subclass status of intrahepatic cholangiocarcinoma, confirmed the significance of the probes for seven enzymes: FH, MAT2B, PLOD2, PLOD1, PDE6D, ALDOC, and NT5DC3." (PMID 40034261, 2025).
invasive breast carcinoma (1 paper, 2019). A carcinoma that infiltrates the breast parenchyma. "Furthermore, the expression of PAI-1 in invasive breast cancer and PLOD2 expression in the corresponding peritumoral adipose tissue were positively correlated with each other." (PMID 31170987, 2019).
ischemic stroke (1 paper, 2017). A stroke disorder caused by obstruction of blood flow to the brain, due to thrombotic (local blood clot formation) or embolic (due to a blood clot or other material traveling from another site) event. "Additionally, PLOD2 was detected to be involved in agiogenesis after ischemic stroke, specifically related to reconstruction of basal lumina, this correlation implies that PLOD2 might be a potential target in anti-angiogenesis treatment." (PMID 28410212, 2017).
kidney cancer (1 paper, 2019). Primary or metastatic malignant neoplasm involving the kidney. "Analysis of PLOD1, PLOD2, and PLOD3 mRNA expression in 20 cancer types (Oncomine dataset) showed significant upregulation and downregulation of the three PLOD isoforms in a number of cancers, including kidney cancer, compared with the corresponding normal tissues." (PMID 31446433, 2019).
lung sarcoma (1 paper, 2025). A malignant mesenchymal neoplasm that arises from the lung. "PLOD2 encodes lysyl hydroxylase, which modifies collagen IV (COLVI), which modifies the extracellular matrix to weaken the lung endothelial barrier, is highly expressed in lung sarcoma metastasis." (PMID 40867253, 2025).
male infertility (1 paper, 2025). The inability of the male to effect fertilization of an ovum after a specified period of unprotected intercourse. "For instance, one study explored the role of IGF2BP2 in male infertility by examining its regulation of PLOD2 mRNA stability." (PMID 40949795, 2025).
neuroblastoma (1 paper, 2024). Neuroblastoma (NB) is the most common solid, extracranial childhood tumor. "Upregulated mRNAs, including SKA3, PLOD2, VIPR2, and GGT5, are implicated in neuroblastoma." (PMID 38892402, 2024).
non-Hodgkin lymphoma (1 paper, 2023). Distinct from Hodgkin lymphoma both morphologically and biologically, non-Hodgkin lymphoma (NHL) is characterized by the absence of Reed-Sternberg cells, can occur at any age, and usually presents as a localized or generalized lymphadenopathy associated with fever and weight loss. "ADH1B, CTH, and PLOD2 showed overexpression in the lymph node tissue of non-Hodgkin lymphoma patients compared to normal lymph node tissue." (PMID 36755971, 2023).
Obesity (1 paper, 2024). Accumulation of substantial excess body fat. "In univariate analyses of obesity-linked systemic factors and PLOD2, significant correlations were found for lean mass (r2 ​= ​0.20), fat mass (r2 ​= ​0.20), serum cholesterol (r2 ​= ​0.17), serum triglycerides (r2 ​= ​0.19) and serum leptin (r2 ​= ​0.10)." (PMID 38694906, 2024).
oesophageal cancer (1 paper, 2025). "PLOD2 is included in gene hypoxia signatures for RCC and is a prognostic marker for patients with oesophageal cancer." (PMID 40867253, 2025).
preeclampsia (1 paper, 2022). Preeclampsia is a hypertensive disorder of pregnancy that is characterized by new-onset hypertension with proteinuria presenting after 20 weeks of gestation, and depending on mild or severe forms may initially present with severe headache, visual disturbances, and hyperreflexia. "HK2, PLOD2, and TREM1 may be associated with the development of pre-eclampsia, and their mechanisms of action in preeclampsia need to be further investigated." (PMID 36541903, 2022). "Interestingly, HK2, PLOD2, and TREM1 were significantly upregulated in the early-onset preeclampsia cohort, and TREM1 was also significantly upregulated in PE patients with concomitant hemolysis, elevated liver enzymes and low platelets (HELLP) complications." (PMID 36541903, 2022).
prostate tumors (1 paper, 2025). "For example, the overexpression of PLOD2 and LOX has been correlated with poor outcomes in multiple cancers, and their detection in prostate tumors may help stratify patients who would benefit from more aggressive treatments or ECM-targeting therapies." (PMID 40943497, 2025).
rectal cancer (1 paper, 2021). A primary or metastatic malignant neoplasm that affects the rectum. "Changes in the alternative splicing of the procollagen-lysine PLOD2, which catalyses the deposition and cross-link of collagens in the extracellular matrix, have been intimately linked to EMT progression and cervical, breast, lung, colon and rectal cancer prognosis." (PMID 33845831, 2021).
sarcoidosis (1 paper, 2025). Sarcoidosis is a multisystemic disorder of unknown cause characterized by the formation of immune granulomas in involved organs. "Reanalysis of a sarcoidosis scRNA-seq dataset revealed that, similar to NL and NXG, sarcoidosis lesional fibroblasts expressed high levels of MHC (e.g., HLA-B and HLA-DRA), CD74, PLOD2, STAT1, TNC, PRSS23, PSMB9, and CXCL9." (PMID 39989459, 2025).
Sepsis (1 paper, 2020). Sepsis is defined as life-threatening organ dysfunction caused by a dysregulated host response to infection. "The profile of MYL9 associated gene interactions for adult sepsis is quite different than that for pediatric sepsis, with association instead with platelet membrane glycoproteins GP5 and GP6, PLOD2, COL6A3, and PROS1." (PMID 32318053, 2020).